YAP1 (Yes1 associated transcriptional regulator)
Diseases named in the same sentence as YAP1 in open-access papers (continued):
Sharing a sentence is not in itself a finding about the gene and the disease.
prostate carcinoma (continued). "In the prostate cancer microenvironment, multi-level evidence supports a YAP1-centered trajectory of CAF evolution that can be conceptualized in three steps: origin (normal fibroblasts, NFs → CAFs), maturation (early → late myCAFs), and functional reprogramming (ECM-CAFs → Lym-CAFs)." (PMID 41514658, 2025). "Despite the role of YAP1 in prostate cancer is well‐established, it is unclear whether it is also involved in BPH progression." (PMID 38050650, 2024). "YAP1 has the ability to bind with TEAD and recruit nerves by activating the transcription of the neural growth factor NGF, and research indicates a significant correlation between the occurrence of PNI in prostate cancer and the expression level of YAP1 in tumor tissues." (PMID 38567163, 2024). "YAP1 overexpression contributes to the induction of cancer stemness in prostate cancer." (PMID 37744228, 2023). "ANKHD1, a positive regulator of YAP1, is overexpressed in prostate cancer cells." (PMID 37282627, 2023). "YAP1 mRNA was upregulated in androgen-insensitive prostate cancer cells, but the mechanism of their interaction is largely unknown." (PMID 36479120, 2022). "Combined treatment with two kinds of drugs, namely, the histone deacetylase inhibitory activity of valproic acid (VPA) and simvastatin (SIM), could inhibit the maintenance and progression of CSCs in prostate cancer by inhibiting YAP1." (PMID 35672802, 2022). "Because GV1001, as a new GnRHR ligand and a YAP1 inhibitor, represents a potential therapeutic for prostate cancer without causing cancer cell migration and metastasis by AR depletion." (PMID 34743733, 2021). "Taken together, these results suggest that YAP1 might be a crucial factor involved in the development of enzalutamide resistance and can be an alternative therapeutic target in prostate cancer." (PMID 33664454, 2021). "Collectively, these observations suggest a new paradigm that GnRHR-driven inactivation of the YAP1-AR axis could be a therapeutic target for prostate cancer." (PMID 34743733, 2021). "This suggests that miR-375 may indeed be a regulator of Hippo signaling in prostate cancer cells alongside the fact that YAP1 expression is reduced in prostate cancer (Human Protein Atlas)." (PMID 32645914, 2020). "Therefore, we believed that there was a high expression of YAP1 in both epithelial cells and stromal cells in prostate cancer tissues." (PMID 32066485, 2020). "There are many reports that YAP1 is upregulated in prostate cancer epithelial cells." (PMID 32066485, 2020). "YAP1 is the most studied YAP isoform, and aberrant YAP1 activation is associated with the etiology of various malignancies including stomach, thyroid, lung, colon, head and neck ovarian, liver, and prostate cancer." (PMID 32292603, 2020). "We examined TrampC1 and RM1 after treatment with the fibroblast-conditioned medium and found that the expression of E-cadherin was decreased in the prostate cancer epithelial cells and that the expression of N-cadherin and vimentin was increased due to the upregulation of YAP1." (PMID 32066485, 2020). "As a result, detecting the expression level of YAP1 in prostate cancer stromal cells may be an early indicator for the disease prognosis." (PMID 32066485, 2020). "In summary, we confirmed a new mechanism of YAP1 in the prostate cancer stroma." (PMID 32066485, 2020). "Decreased YAP1 may lead to distorted Hippo signaling and may render advanced prostate cancer impervious to the modulators of the Hippo signaling." (PMID 31835563, 2019). "The YAP1–AR axis appears to play a role in prostate cancer progression." (PMID 31835563, 2019). "Hippo signaling modulates cellular functions by regulating the phosphorylation of YAP1; thus, decreased YAP1 expression in prostate cancer cells might render prostate cancer cells resistant to modulation of the Hippo pathway." (PMID 31835563, 2019). "The corresponding gene, YAP1, is a tumor-suppressor gene that plays a role in prostate cancer." (PMID 28984208, 2017).
prostate carcinoma (continued). "In addition, we showed that YAP1 plays a critical role in regulating proliferation of prostate cancer progenitor-like cells to contribute to the growth of CRPCa." (PMID 29383141, 2017). "Finally, the knock down of YAP1 expression or the inhibition of YAP1 function by Verteporfin in TRAMP prostate cancer mice significantly suppresses tumor recurrence following castration." (PMID 29383141, 2017). "In addition, we examined expression levels of the two miR-375 target genes (SEC23A and YAP1) and observed significant reduction in the expression at both protein and mRNA levels in miR-375 transfected prostate cancer cell lines." (PMID 27832783, 2016). "High protein expression of YAP1 and SRC are commonly observed in high Gleason grade prostate cancer clinical specimens, and positively correlates with a poor prognosis and metastatic burden, indicating that YAP1 and SRC may provide valuable therapeutic targets and warrant further investigation." (PMID 36671452, 2022). "Thus, increased levels of HOXC4 in prostate cancer may promote tumorigenesis via upregulation of YAP1." (PMID 32012197, 2020). "One study demonstrates that unlike in hormone-sensitive prostate cancer cells, YAP1-AR interactions are androgen-insensitive and may cause resistance to enzalutamide in mCRPC cells." (PMID 32292603, 2020). "Importantly, this level of WSS regulates YAP1 activity to drive motility of prostate cancer cells." (PMID 28098159, 2017). "In vivo, selective depletion of YAP1 in ECM-CAFs led to slower tumor progression, increased infiltration of CD8+; T-cells, and reduced collagen deposition in prostate cancer mouse models." (PMID 41228234, 2025). "It promotes aggressive behavior in NSCLC and prostate cancer via activation of ERK/MYC and STAT3 signaling, respectively, while in medullary thyroid carcinoma, it correlates with nodal spread through YAP1 suppression." (PMID 40940980, 2025). "Relative to benign prostatic hyperplasia, stromal YAP1, FAP, and α-SMA levels were higher in prostate cancer, with substantial spatial overlap between YAP1 staining and the CAF marker FAP." (PMID 41514658, 2025). "Similar ceRNA-driven mechanisms involving miR-376a-3p/YAP1 in glioma, miR-590-5p/METTL3 in lung adenocarcinoma, and miR-376a-3p/PRMT5 in prostate cancer further underscore its oncogenic potential." (PMID 40903777, 2025). "A recent study indicated the potential role of YAP1 in regulating the infiltration of MDSCs and CD8+ T cells in prostate cancer." (PMID 39630608, 2024). "The transcriptional co-activator YAP1 and its paralog TAZ have been found to be overexpressed in prostate cancer, establishing a pro-tumorigenic phenotype which is attenuated upon YAP/TAZ knockdown." (PMID 35954292, 2022). "In prostate cancer cell lines, ANKHD1 is a positive regulator of YAP1 and promotes cell growth and cell cycle progression by promoting cyclin A." (PMID 34235216, 2021). "Pharmacological inhibition of YAP1 nuclear translocation drastically reduced FSTL3 expression and a positive correlation between YAP1 and FSTL3 mRNA expression was very recently shown in prostate cancer." (PMID 34395416, 2021). "This study demonstrates the role of YAP1, TEAD1 and SRC in the conversion of NFs to CAFs in prostate cancer." (PMID 32066485, 2020). "The link between YAP1 and SRC in prostate cancer specifically indicates that the prostate cancer stroma has not been explicitly implicated." (PMID 32066485, 2020). "The results revealed that FER1L4 control prostate cancer proliferation and apoptosis via upregulation of FBXW7 and downregulation of YAP1 and its target gene expression." (PMID 32140077, 2020). "As an example, the YAP1 (Yes-associated protein)/TAZ (transcriptional coactivator with PDZ-binding motif) are reported to play an important role in tumor initiation and cancer progression, and may be proposed as prognostic biomarker in gastric, breast, ovarian, renal and prostate cancers." (PMID 30642298, 2019).
prostate carcinoma (continued). "Total TAZ protein level was also slightly elevated, suggesting that YAP1 and TAZ activity are both stimulated by WSS in prostate cancer cells." (PMID 28098159, 2017). "By contrast, transcript-level silencing of YAP1 and WWTR1 has been reported in hematological cancers such as multiple myeloma (MM) and NE cancers such as medullary thyroid cancer, NE prostate cancer, and small cell lung cancer (SCLC)." (PMID 36719743, 2023). "This makes YAP1 expression analysis a universally applicable prognostic feature that is not dependent on a particular molecular prostate cancer subtype." (PMID 32488048, 2020). "Hyperactivation of YAP1 signaling was reported in prostate cancer due to epigenetic modification and altered expression of non-coding RNAs." (PMID 32140077, 2020). "Given that ERG is able to antagonize AR function in prostate cancer cells, it will be interesting to explore whether ERG regulation of YAP1 also relies on antagonizing the repressing actions of the AR/DNMT3a complex." (PMID 29383141, 2017). "Consequently, androgen deprivation therapy can induce YAP1 expression, which in turn regulates downstream factors such as SOX2 and Nanog to promote PCa stem/progenitor like cells and contribute to castration resistant prostate cancer growth." (PMID 29383141, 2017). "However, the mechanism of action of YAP1 in prostate cancer stromal cells is not clear." (PMID 32066485, 2020). "We found that PDEF-PC3 and PDEF-DU145 cells have higher YAP1 protein levels as compared to VC-PC3/VC-DU145 cells, suggesting that YAP1 levels can be restored by PDEF, which may, as such, re-sensitize the advanced prostate cancers to regulators of the Hippo signaling pathway." (PMID 31835563, 2019). "The protein levels of YAP1, SLC1A5, and GLS1 in benign prostatic hyperplasia (BPH), prostate cancer (PCa) that did not progress to CRPC, and CRPC tissue samples were evaluated using western blotting." (PMID 37773303, 2024).
glioma (79 papers, 2014 to 2025). A benign or malignant brain and spinal cord tumor that arises from glial cells (astrocytes, oligodendrocytes, ependymal cells). "Further, ROS levels were shown to activate Drosophila Yorkie or its mammalian ortholog YAP1 (Yes-associated protein 1) in Drosophila enterocytes and human glioma cell lines." (PMID 41367496, 2025). "A study demonstrated that Yes-associated protein 1 (YAP1) promotes the metastasis of U251 glioma cells by upregulating Jagged-1 (JAG1) expression and activating the Notch signal pathway." (PMID 38474320, 2024). "Another FDA-approved TCA, imipramine, suppressed tumor progression in glioma cell lines and mouse models by inhibiting the activity of the oncogenic yes-associated protein 1 (YAP1)." (PMID 37377607, 2023). "In our previous study, we reported that up-regulated YAP1 in human gliomas is positively associated with glioma patient prognosis and transient over-expression of YAP promotes glioma cell proliferation." (PMID 28962630, 2017). "YAP1 deficiency has been shown to promote healthy aging in Caenorhabditis elegans, while YAP1 inhibits cellular senescence in human fibroblasts, mesenchymal stem cells, periodontal ligament stem cells, glioma cells, and hepatic stellate cells." (PMID 40468463, 2025). "Among other signaling pathways, ROS levels were shown to activate Drosophila Yorkie or its mammalian ortholog YAP1 (Yes-associated protein 1) in Drosophila enterocytes and human glioma cell lines, a molecule which has been shown to be directly upregulating tissue proliferation." (PMID 41367496, 2025). "Based on four signature genes (AHR, DACH1, MGMT, and YAP1), a risk model for predicting glioma sensitivity to temozolomide was constructed, and the results of timeROC in both the training and validation sets showed that the model had good predictive performance." (PMID 36959804, 2023). "Upon treatment with dipyridamole, human U87 glioma cells decreased cell viability, clonogenic colonization, migration, and invasion, along with Noxa upregulation, Endoplasmic Reticulum (ER) stress, impaired autophagic flux, Yes-associated Protein 1 (YAP1) phosphorylation, and YAP1 reduction." (PMID 35054765, 2022). "In addition, high YAP1 expression glioma is more aggressive and is associated with poor outcomes." (PMID 33336871, 2021). "PTEN deletion in gliomas activates YAP1, which upregulates LOX expression, leading to macrophage recruitment to the tumor microenvironment through the β1 integrin-PYK2 pathway, enhancing glioma survival and angiogenesis." (PMID 41551155, 2025). "Overexpression of miR-376a leads to the inhibition of SIRT1, YAP1 (Yes-associated protein 1), and VEGF (Vascular Endothelial Growth Factor) expression, consequently suppressing the proliferation, migration, and angiogenesis of glioma cell lines." (PMID 40710366, 2025). "Although the data support a model in which the NUTM2A‐AS1/miR‐376a‐3p/YAP1 axis contributes to glioma progression, further in vivo studies are required to fully elucidate this regulatory network." (PMID 40903777, 2025). "In colorectal cancer, transcriptional activation via H3K27 acetylation permits NUTM2A-AS1 to sequester miR-126-5p, leading to upregulation of FAM3C, while in glioma, its interaction with miR-376a-3p regulates YAP1 expression." (PMID 40903777, 2025). "In conclusion, silencing of lncRNA NUTM2A-AS1 inhibited proliferation and induced apoptosis in human glioma cells via the miR-376a-3p/YAP1 axis." (PMID 38730506, 2024). "Over-expression of miR-376a-3p significantly inhibited proliferation and induced apoptosis in glioma cells through down-regulating YAP1 expression." (PMID 38730506, 2024).
glioma (continued). "The results showed that YAP1 expression was significantly higher in glioma cell lines incuding U251, T98-G and A172 cells than in HEB cell lines." (PMID 38730506, 2024). "Previous studies have found that YAP1 can bind to miRNAs, such as miR-622, miR-27b-3p and miR-195-5p, which are involved in regulating the proliferation, apoptosis and migration of glioma cell lines." (PMID 38730506, 2024). "The expression of lncRNA NUTM2A-AS1, miR-376a-3p, and YAP1 in human glioma cell lines was detected by qRT-PCR." (PMID 38730506, 2024). "Downregulation of lncRNA NUTM2A-AS1 plays a protective role in glioma through inhibiting proliferation and inducing apoptosis in human glioma cells via the regulation of miR-376a-3p/YAP1 axis." (PMID 38730506, 2024). "YAP‐1 was highly expressed in 62 (31.0%) and lowly expressed in 138 (69.0%) of the 200 gliomas in a tissue microarray." (PMID 38925618, 2024). "In summary, lncRNA NUTM2A-AS1 down-regulation inhibits glioma cell proliferation and induces glioma cell apoptosis by regulating the miR-376a-3p/YAP1 axis." (PMID 38730506, 2024). "The findings suggested that lncRNA NUTM2A-AS1 positively regulates of YAP1 expression in human glioma cells." (PMID 38730506, 2024). "Further mechanistic studies suggested that miR-376a-3p reduced glioma cell proliferation and increased apoptosis by inhibiting YAP1 expression." (PMID 38730506, 2024). "Our data further give support to those demonstrating that TAZ knockdown reduced SNB19 human glioma cell migration, likely due to impaired interaction with YAP1." (PMID 39718433, 2024). "Next, we examined the expression levels of YAP1 in glioma cell lines (U251, T98-G, A172) by qRT-PCR." (PMID 38730506, 2024). "This activation of the YAP1 signalling pathway encourages macrophage infiltration into the tumor microenvironment in glioma cells, contributing to glioma progression." (PMID 39075555, 2024). "In PTEN-null glioma, YAP1 is activated, upregulating lysyl oxidase expression (LOX) in glioma cells." (PMID 37012233, 2023). "The expression level of YAP1 was positively correlated with the grade of glioma, which promotes the proliferation and invasion of glioma cells." (PMID 37423952, 2023). "And, in the future, there will be more research on the carcinogenic role of YAP1 in glioma, which is expected to achieve targeted personalized treatment of glioma patients with YAP1." (PMID 35350840, 2022). "The results showed that high expressions of MT1-MMP, β1-integrin and YAP1 were found in glioblastoma (GBM) compared with lower-grade glioma (LGG)." (PMID 35350840, 2022). "YAP1 also plays an active role in glioma cell proliferation, migration, and apoptosis under microRNA and long noncoding RNA control." (PMID 35054765, 2022). "The relationship betweenthe expression of MT1-MMP, β1-integrin and YAP1 in gliomas and prognosis was verified by GEPIA." (PMID 35350840, 2022). "In order to further explain the role of MT1-MMP, β1-integrin, YAP1 in glioma, we examined the relationship between three proteins and Ki-67." (PMID 35350840, 2022). "Metformin induced YAP1 phosphorylation to abolish the YAP1-dependent stem-like properties in glioma." (PMID 36289774, 2022). "The purpose of this study was to investigate the effects of MT1-MMP, β1-integrin and YAP1 on the prognosis of gliomas." (PMID 35350840, 2022). "High levels of nuclear YAP1 immunoreactivity were detected in GBM tissues, and it was shown that silencing of YAP1 in glioma cell lines led to a significant reduction in cell growth." (PMID 36010607, 2022). "In one of the studies, the authors analyzed the expression of YAP1 in 117 clinical samples of glioma, as indicated by the 2016 WHO classification, and demonstrated that YAP1 is strongly correlated with glioma molecular subtypes and patient prognosis." (PMID 35884733, 2022). "In glioma cells, PTEN deficiency fosters activation of yes-associated protein 1 (YAP1), which modulates the protein-lysine 6-oxidase (LOX)." (PMID 34687436, 2022).